FLT3 (fms related receptor tyrosine kinase 3)
Diseases named in the same sentence as FLT3 in open-access papers (continued):
Sharing a sentence is not in itself a finding about the gene and the disease.
leukemia (continued). "Compared with the control, BIO augmented the proportion of MV4-11 cells in G0/G1-phase, and reduced the proportion of cells in S-phase and G2/M-phase, indicating that BIO-induced G1 cell cycle arrest in FLT3-ITD mutated leukemia cells." (PMID 36481875, 2022). "Both FLT3 mutations and FLT3 expression levels have been used as biological markers for diagnosis and evaluation of the prognosis of leukemia." (PMID 36297550, 2022). "NUP98-NSD1 leukemias are frequently associated with FLT3 -ITD and/or WT1 mutations, which occur in about 80% and 50% of cases, respectively, possibly adding to the poor prognosis associated with these cases." (PMID 34204358, 2021). "BCR-ABL1 and hyperactive FLT3 are tyrosine kinases that causally contribute to the development of leukemia and induce RAF1 and BCL-XL." (PMID 34298678, 2021). "In previous studies, FLT3 was found to be a late acquired genetic change; our results revealed two molecular collaborative patterns of FLT3 mutation in leukemia progression." (PMID 33836835, 2021). "METHODS: Murine Ba/F3 leukemia cell lines were stably transfected with distinct FLT3-ITD variants resulting in IL3-independent growth." (PMID 34831215, 2021). "WT1 mutations are frequently found in de novo AML, especially in younger patients and in FLT3-ITD or CEBPA mutated leukemias." (PMID 33917307, 2021). "This and our recent reports highlight how distinct mechanisms of miR-126 dysregulation driven by specific leukemogenic mutations (i.e., CBFB-MYH11, BCR-ABL, FLT3-ITD) play a relevant role in leukemia pathobiology." (PMID 34686664, 2021). "Expression of FLT3-TKD is insufficient to trigger leukemia in mice; however, a co-NPM1 mutation actively led to the onset of AML in mice." (PMID 33836835, 2021). "Our findings suggest the possibility of a new therapeutic option, the anti-CD52 antibody alemtuzumab, to treat leukemia carrying the FLT3-ITD mutation." (PMID 34035227, 2021). "The allelic ratio reflects the clonal burden of the FLT3 ITD-mutated cells within the leukemia cell population." (PMID 33816294, 2021). "The combination of 1D11 with plerixafor and cytarabine decreased leukemia burden in a murine FLT3-mutated AML mouse model." (PMID 34012921, 2021). "Glycolytic inhibitors such as 3-Bromopyruvate propyl ester (3-BrOP) and 2-deoxyglucose (2-DG) exhibited cytotoxicity in murine and human leukemia cells carrying FLT3/ITD mutation." (PMID 34150668, 2021). "Autophagy and ATF4 play a key role in FLT3-ITD mutation mediated leukemia proliferation and survival." (PMID 32312983, 2020). "Overall, these results indicated that the synergistic antitumor effects of cotreatment with AC220 and DAPT were restricted to FLT3/ITD-mutated leukemia cells." (PMID 32296014, 2020). "Fifty percent of patients with mutant FLT3 achieved composite CR (CR plus CRi plus CR with incomplete platelet recovery) with an ORR (CR plus CRi plus morphologic leukemia-free state) of 88% in FLT3-mutated patients." (PMID 33127875, 2020). "We used both in vitro and in vivo studies to investigate the effects of combination of Gilteritinib with ATO at low concentration on FLT3-ITD positive leukemias, together with the underlying molecular mechanisms of these processes." (PMID 32565734, 2020). "Taken together, mutations of FLT3 follow leukaemia-initiating events during the course of AML development." (PMID 33003568, 2020). "Particularly, the evaluation of the FLT3 allelic ratio (AR) has been included in the European leukemia net (ELN) classification to further improve risk stratification in FLT3-ITD mutated AML patients, even if this remains a matter of debate." (PMID 32796597, 2020).
leukemia (continued). "A fourth study was based on the development of leukemia through transformation of murine hematopoietic stem/progenitor cells with IDH2 mutants in cooperation with FLT3-ITD or NRAS mutant alleles." (PMID 32859092, 2020). "FLT3 mutations are associated with polyunsaturated fatty acid metabolism, and they play a previously underappreciated role in obesity-related leukemia." (PMID 32337264, 2020). "This NUP98-NSD1-positive PDX model was analyzed in the 6th transplantation and showed AML with normal karyotype, while it was wildtype for genes frequently mutated in leukemia, such as FLT3, NRAS, NPM1, IDH1/2, and DNMT3A." (PMID 32993115, 2020). "Further investigations in a larger population or animal models focusing on the role of AXL in the pathophysiologic process of Flt3-mutated leukemia is warranted its significance on clinical outcomes." (PMID 33363015, 2020). "Further underscoring this, and in sharp contrast to its role in AML, on the background of the APL-typical PML-RARA fusion, the Flt3-ITD mutation reduced the inhibitory effect of atRA on the ability to initiate leukemia in secondary recipients." (PMID 32998330, 2020). "Glycolytic inhibitors cause severe ATP depletion and massive cell death in FLT3/ITD positive leukemia cells." (PMID 32641978, 2020). "To better address the specificity of the synergy between TKIs and GSIs, we generated isogenic clones carrying the FLT3/ITD mutation in the SKM-1 leukemia cell line, with a 21-bp ITD fragment knocked in using the CRISPR/Cas9 system." (PMID 32296014, 2020). "A major limitation in the treatment of FLT3-mutated AML by FLT3 inhibitor monotherapy is leukaemia relapse that often occurs within months after initial remission." (PMID 32102366, 2020). "It was also found that FLT3-mutated patients when compared with FLT3-unmutated had higher relapse incidence (RI) and lower leukemia-free survival (LFS) even after Allo-SCT." (PMID 32333156, 2020). "Recently, the use of sorafenib in the post-transplant setting has been found to improve leukemia-free survival and the overall survival of patients with FLT3-mutated AML." (PMID 33212779, 2020). "FLT3 inhibitors have been approved for the treatment of this AML subtype but leukaemia relapse remains to be a major cause of treatment failure." (PMID 32102366, 2020). "In clinical practice, a recurrent phenomenon in patients receiving FLT3 inhibitors is the emergence of leukaemia clones carrying FLT3-TKD mutations at relapse." (PMID 32102366, 2020). "About 30% of AML patients harbor a mutation in the Fms-Like Tyrosine Kinase 3 (FLT3), which makes the leukemia more aggressive." (PMID 30686755, 2019). "A significantly higher CXCR4 RFI was detected on the surface of leukemia cells in the FLT3-ITD mutated AML group (9.24 ± 5.51, mean ± SD) than in the FLT3-wt group (5.72 ± 4.44, P ≤ 0.0001)." (PMID 31434952, 2019). "We found that a high PD-L1 expression on leukemia blasts predicts for worse overall survival (OS), specifically in patients with internal tandem duplications in FLT3 (FLT3-ITD) and with mutated NPM1." (PMID 31185600, 2019). "A recent study demonstrated production of IL-15 by leukemia cells in patients with FLT3 mutations treated with Sorafenib, a tyrosine kinsase inhibitor which targets mutant FLT3, similar to Midostaurin." (PMID 31781488, 2019). "Consistent with this, 2-deoxy-d-glucose (2-DG) and 3-Bromopyruvate propyl ester (3-BrOP), inhibitors of the glycolytic enzyme hexokinase, were found to synergize with sorafenib in killing leukemia cells with FLT3/ITD mutation." (PMID 30947742, 2019). "Potent inhibitory growth effects on leukemia cells with FLT3 mutations were achieved by inhibition of the FLT3 kinase, with subsequent down-regulation of phosphorylated-FLT3/STAT5, G1 arrest, and apoptosis." (PMID 31035676, 2019). "Our study is the first to evaluate the resistance of FLT3/ITD-mutated leukemia cells to a tyrosine kinase inhibitor based on metabolomic study." (PMID 30947742, 2019).
leukemia (continued). "The results showed that the level of CXCR4 expression was related to the presence of FLT3‐ITD mutations in leukemia blasts." (PMID 31518054, 2019). "By doing so, STAT5 activation promotes an overall elevation of ROS level, which acts as a feed-forward loop, especially in high risk Fms-related tyrosine kinase 3 (FLT3) mutant leukemia." (PMID 30262727, 2018). "Intriguingly, while SIRT1 was shown to regulate c-MYC in Flt3-ITD mutated leukemia, it has been demonstrated to regulate Mxd1 in malignant melanoma." (PMID 30420889, 2018). "The significance of FLT3 in leukemia has been thoroughly investigated, and the population of the FLT3 mutations was reported to be approximately 1/3 of all AML patients." (PMID 29416667, 2018). "The relationship between HLH and some subtypes of leukemia such as FLT3-ITD and/or DNMT3A mutations is unclear." (PMID 29843647, 2018). "Sorafenib combined with allo-HSCT induced a lower relapse rate and longer leukemia-free survival (LFS) in patients with FLT3/ITD-mutated AML." (PMID 30514344, 2018). "Our findings highlight the potential benefit of targeting poor prognosis acute B‐cell progenitor leukaemia and ETP leukaemia with recurrent FLT3 mutations using clinical FLT3 inhibitors." (PMID 30596405, 2018). "In preclinical studies, ponatinib had significant anti-leukemia activity against AML specimens with FLT3–ITD or TKD mutations, including the F691I gatekeeper." (PMID 29209600, 2017). "We demonstrate that efficacy of TKI therapy in FLT3-mutated AML is highly dependent on the mutational landscape within each leukemia and provide a valuable framework for designing rational combination therapy in FLT3-ITD AML." (PMID 29312564, 2017). "FLT3-mutated AML is a particularly high-risk leukemia subtype in both adults and children, and the potential for selective FLT3 inhibitors to decrease relapse risk and improve cure rates is alluring." (PMID 29209600, 2017). "Another FLT3 inhibitor, TTT-3002, demonstrated high potency in FLT3/ITD and FLT3/D835 mutated leukemia cell lines and patient samples in preclinical studies." (PMID 28077790, 2017). "FLT3 mutations function as oncogenic drivers in both mouse models of leukemia and human AML cells, and therefore represent important therapeutic targets." (PMID 27329844, 2016). "We propose a novel stem cell-like leukemia termed GATA3low ETP-ALL with a high frequency of FLT3 mutations as a distinct molecular entity with sensitivity to hypomethylating agents." (PMID 27658391, 2016). "Until now, the observation of an increased outgrowth of FLT3/ITD AML in NOD/SCID mice suggests that in a large part of the FLT3/ITD-positive leukemia, the mutation is present at the level of the malignant stem cell." (PMID 27465508, 2016). "A small FLT3-TKD-mutated subclone (<10%) of the primary leukemia survived chemotherapy and underwent expansion at relapse (25-30%)." (PMID 27462774, 2016). "We generated isogenic leukemia cell clones in which the FLT3 gene was disrupted in a single allele using TALENs." (PMID 26669855, 2015). "In this study, we generated isogenic clones, in two individual leukemia cell lines, by disrupting FMS-like tyrosine kinase 3 (FLT3) gene in a single allele using designed TALENs." (PMID 26669855, 2015). "Previous studies have demonstrated MLL-AF4 leukemias to have fewer additional mutations as compared to other leukemias, but have identified N-Ras, K-Ras, and Flt-3 as a source of potential cooperating mutations." (PMID 26351841, 2015). "This pathway represents a promising target for leukemia therapy, because it is frequently activated in various leukemias, including FLT3-mutated AML, and thought to correlate with poor prognosis and drug resistance." (PMID 25826077, 2015). "Mutations in FLT3 lead to constitutively active FLT3 which can then act in a ligand-independent manner in leukemia." (PMID 24658394, 2014).
leukemia (continued). "The identification of FLT3 aberrancies in high-risk subsets of leukemia patients was discovered two decades ago, and much has been learned about the biology, clinical implications, and targeting possibilities." (PMID 25295230, 2014). "This review will summarize the biology of FLT3 in leukemia, and discuss the benefits and hindrances associated with FLT3 inhibitor therapy." (PMID 25295230, 2014). "In a knock-in mouse model, the combination of Npm1c and Flt3-ITD caused universal leukaemia, with all mice becoming moribund in 31–68 days." (PMID 25056697, 2014). "Acquired CN-LOH or uniparental disomy, is seen in leukemia with loss of the normal allele and duplication of the mutant allele, such as seen with FLT3-ITD mutations." (PMID 25295230, 2014). "Based on the pre-clinical data in pediatric leukemia with either activating FLT3 mutations or overexpression, lestaurtinib was moved into pediatric trials." (PMID 25295230, 2014). "In adults with normal cytogenetic AML, NPMI1 mutations are associated with high HOX expression and those leukemias have a higher frequency of FLT3 mutations." (PMID 25539595, 2014). "Of specific relevance for human AML, in leukemia driven by both NPM1c and a FLT3 activating mutation a highly significant survival advantage was demonstrated (P=0.008)." (PMID 24220271, 2014). "FMS-like tyrosine kinase 3 (FLT3) represents another attractive target, given its overexpression on the majority of leukemia cells and the high rate of FLT3 mutations in human leukemia." (PMID 25295230, 2014). "Homozygosity of JAK2 V617F and of FLT3 mutations is associated with a poorer prognosis of patients with leukemia or myeloproliferative disorders." (PMID 25373456, 2014). "The analysis of FLT3 mutational status and of the leukemia-initiating cell population allowed to define the clonal changes occurring during the development of sorafenib resistance." (PMID 23936658, 2013). "To this end, we utilized a murine model of FLT3-mutated AML by transplanting mice with Ba/F3-ITD-luciferase leukemia cells known to engraft primarily in the BM of mice with secondary dissemination to the spleen and other organs." (PMID 23826077, 2013). "This putative normal HSC, CD34+CD38– ALDHbright, cell population of 7 of these 19 CD34-positive AML cases was essentially devoid of cells with the leukemia-specific cytogenetic abnormalities FLT3-ITD and/or mutated NPM1." (PMID 24244383, 2013). "The understanding of the signaling of WT and mutated FLT3 is essential to understand the mechanisms through which this receptor contributes to leukemia development." (PMID 23936658, 2013). "In FLT3-associated leukemia patients, the antiproliferative effect of quizartinib was inconsistent – with refractory as well as sensitive cases identified." (PMID 23497317, 2013). "Sorafenib, originally developed as a B-RAF inhibitor, also inhibits FLT3 and is selectively cytotoxic to leukemia cells harboring FLT3 mutations." (PMID 23847761, 2013). "Another gene specifically upregulated in MLL-rearranged leukemias that has been proposed to play a critical role in their pathogenesis is the gene encoding Fms-like tyrosine kinase 3 (FLT3)." (PMID 23977266, 2013). "This compound was found to inhibit growth and survival of patient-derived leukemia cells, associated with a reduction in levels of phosphorylated FLT3 and inhibition of downstream effectors such as ERK and MEK." (PMID 23847761, 2013). "The study of six normal karyotype AMLs with FLT3-ITD mutations allowed to propose a clonal model of evolution of these leukemias and to propose the timing of acquisition of these mutations during the natural history of development of the leukemic process." (PMID 23936658, 2013).
leukemia (continued). "This difference in leukemia subtype, suggests that the presence of a FLT3/ITD mutation in this system results in the transformation of very early myeloid precursors that are impaired in maturation." (PMID 22643831, 2012). "Although FLT3 activating mutations occur rarely in lymphoid leukemia, they occur at a higher frequency in subtypes of childhood leukemia such as hyperdiploid and MLL rearranged ALL." (PMID 22643831, 2012). "The induction of a biphenotypic leukemia in this model would be surprising given the clinical data documenting the role of both Nup98 translocations and FLT3/ITD mutations in myeloid disease." (PMID 22643831, 2012). "Point mutations in kinase domains of RTKs such as EGFR, HER2, MET, KIT, and FLT3 (among others) have been implicated as driver mutations in various cancers such as lung, breast, renal, liver, intestinal, and leukemia." (PMID 22347506, 2012). "Disturbance of FLT3 through over-expression or constitutive activation by FLT3 activating mutations can result in leukemias with promiscuous lineage properties." (PMID 22643831, 2012). "This was similar to the response of MV4-11, a human leukemia cell line with a FLT3 ITD mutation and documented sensitivity to lestaurtinib." (PMID 21272320, 2011). "We have demonstrated that both canine and human leukemias share FLT3 ITD mutations, in agreement with a previous report." (PMID 21272320, 2011). "FMS-like tyrosine kinase 3 (FLT3), one of the most commonly mutated genes in human leukemias, is a class III receptor tyrosine kinase that is an important regulatory gene involved in normal hematopoiesis." (PMID 21272320, 2011). "To gain a global view of oncogenic FLT3 signaling in human leukemia cells, we applied PhosphoScan®, an immunoaffinity-MS profiling approach to leukemia cell lines containing activated FLT3 mutations (FLT3-ITD and amplification)." (PMID 21552520, 2011). "The absolute incidence of FLT3 mutations in pediatric leukemia is of interest in part because of the existence of several promising FLT3 inhibitors currently under development such inhibitors are more effective in the presence of FLT3 activation." (PMID 20875128, 2010). "The highest rates of FLT3 mutation were recorded in population series of leukemias in Japan (9% of 162 ALL patients) and Sweden, with 8% of ALL and 21% of AMLs (in children up to age 17 yrs)." (PMID 20875128, 2010). "Mutations in FLT3 result in activated tyrosine kinase activity, cell growth stimulation, and a poor prognosis among various subtypes of leukemia." (PMID 20875128, 2010). "Most leukemias were of cytogenetically normal (CN) intermediate-risk cytogenetics (76%) with half of those expressing FLT3-ITD." (PMID 21048955, 2010). "We evaluated the prevalence and timing of origin of FLT3 mutations in a population series of childhood leukemia patients from Northern California." (PMID 20875128, 2010). "Using NCCLS bone marrow samples, we have screened for FLT3 mutations in the largest sample of pediatric leukemias yet reported." (PMID 20875128, 2010). "It is known that FLT3 is a leukemia oncogene and activating FLT3 mutations are likely to contribute in the development of leukemia in humans." (PMID 19330068, 2008). "Furthermore, the canine GL-1 cell line was found to be sensitive to the FLT3 inhibitor lestaurtinib, similar to the human leukemia cell line MV4-11 carrying a comparable FLT3 mutation." (PMID 40563676, 2025). "Patients with FLT3-ITD mutated AML have a high burden of leukemia and poor prognosis." (PMID 40092706, 2025). "Notably, BET bromodomain inhibition has been utilized in concert with TK inhibitors to overcome resistance-driving mutations in leukemia, and combinations of FLT3 and BET bromodomain inhibitors delivered as separate compounds are being explored as therapies." (PMID 40153395, 2025).